ERBB2 (erb-b2 receptor tyrosine kinase 2)
Diseases named in the same sentence as ERBB2 in open-access papers (continued):
Sharing a sentence is not in itself a finding about the gene and the disease.
breast cancer (continued). "Here we report that deleting LKB1 expression in mammary epithelium harboring activating mutations in ErbB2 promotes increased tumor initiation and enhanced growth of early-stage mammary tumors." (PMID 24280377, 2013). "Amplification and/or overexpression of erbB2 occur in approximately 25 to 30% of invasive breast cancers and are significantly associated with a worse prognosis in breast cancer patients." (PMID 24168763, 2013). "Within the luminal-group, 39 miRNAs were associated with ERBB2 overexpression and 24 with E-cadherin gene mutations, which are frequent in this subtype of breast cancer cell lines." (PMID 23601657, 2013). "In human myocardiocytes in culture, maintenance of ERBB2 is critical for myofibrillar structure and function and therapies used for targeting ERBB2 positive breast cancers are associated with cardiotoxicity." (PMID 23785396, 2013). "The other 3 breast cancer subtypes showed a lower frequency of these mutations: HR+/ERBB2+ in 15/54 (27.8%), HR-/ERBB2+ in 10/43 (23.3%) and HR-/ERBB2- in 16/68 (23.5%)." (PMID 24229379, 2013). "Concerning esophageal and breast cancer, in both of which alcohol consumption is a risk factor and ERBB2 gene amplification was reported." (PMID 24278325, 2013). "Overexpression of the ErbB2/Her2/Neu receptor is observed in 20 to 25% of breast cancer patients and is associated with a poor prognosis." (PMID 23383112, 2013). "Here we demonstrate that loss of LKB1 increases ErbB2-driven mammary tumor initiation and early-stage tumor growth." (PMID 24280377, 2013). "ErbB2 is present in about 25–30% of breast cancer patients and is associated with poor prognosis and high relapse rate." (PMID 23308242, 2013). "In recent years, a systematic investigation of the potential role of inherited germline variants of ERBB2 in breast cancer risk has been conducted using single nucleotide variants and haplotype-based analyses." (PMID 24386251, 2013). "Clinically, overexpression of ErbB2 is associated with approximately 30% of breast cancers, ovarian cancers and other common types of cancers including lung, gastric, and oral cancers." (PMID 24069396, 2013). "Overall, our discovery confirms that loss of LKB1 expression leads to the development of breast cancer and accelerated ErbB2-mediated oncogenesis." (PMID 23451056, 2013). "The most notable overall observation is the lack of evidence to support a significant association between ERBB2 single nucleotide polymorphisms and breast cancer initiation, despite the information supporting its role in breast cancer progression." (PMID 22489125, 2012). "In the molecular classification of breast cancer, tumors which lack ER and PR and overexpress MembErbB-2 (MembErbB-2+/ER-PR-) have been included in the ErbB-2-positive molecular subtype, associated with poor outcome." (PMID 22356700, 2012). "We generated virgin female cohorts that carried one or both conditional FAK alleles, MMTV-Cre and MMTV-activated ErbB2 and monitored these mice for the presence of palpable mammary tumours." (PMID 22373082, 2012). "Previously, we demonstrated that p190B Rho GTPase activating protein (RhoGAP) deficiency inhibits ErbB2-induced mammary tumor formation in mice." (PMID 22582143, 2012). "Given its over-expression in Her2 breast cancers, we further studied the ErbB2/EphrinB1 association in additional breast cancer cell lines." (PMID 22279592, 2012). "In human breast cancer, several studies considering the analysis of ERBB2 gene sequence variants were performed focusing on specific polymorphisms already recognized to be possibly associated with HBC pathology." (PMID 22489125, 2012). "ERBB2 oncogene amplification constitutes one of the most important genetic alterations associated with human breast cancer and was found to be correlated with poor patient prognosis by Slamon and colleagues." (PMID 22253826, 2012).
breast cancer (continued). "Amplification was observed over cancer genes previously implicated in breast cancer development including ERBB2, CCND1, MYC, MDM2, ZNF217, and ZNF703 and a homozygous deletion involving MAP2K4 was identified." (PMID 22608084, 2012). "The independent prognostic value of PIK3CA mutation status in ERBB2-positive breast cancer patients should be now confirmed in larger series of patients included in randomized prospective ERBB2-based clinical trials." (PMID 22330809, 2012). "We analyzed the roles of Epidermal Growth Factor Receptor (EGFR) and Hepatocyte Growth Factor Receptor (Met) in mammary epithelial cells and mammary tumor cells derived from a mutated-ErbB2 transgenic mice." (PMID 23028720, 2012). "One-third of breast cancers display amplifications of the ERBB2 gene encoding the HER2 kinase receptor." (PMID 23033967, 2012). "As far as we know, this is the first attempt to examine ERBB2 genetic variations in cat mammary genome and its possible association with the onset and progression of cat mammary tumors." (PMID 22489125, 2012). "Levels of the ErbB2 splice variant are only 5% of those observed with the wildtype receptor, both in primary normal breast tissue and breast cancers." (PMID 22007291, 2012). "Increased IGF-I signaling has also been linked to trastuzumab resistance in ErbB2 positive breast cancer and blocking both the IGF-I receptor (IGF-IR) and the ErbB2 receptor (ErbB2-R) inhibits ErbB2 driven breast cancer cell growth." (PMID 21867536, 2011). "ERBB2, overexpressed in 25 to 30% of human breast cancers, is associated with metastasis, and ERBB2-overexpressing cells are self-sufficient with respect to, anchorage-independent growth and efficient in invasion." (PMID 21731642, 2011). "Recent work in mouse models of neu/ERBB2-induced breast cancer has underlined STAT1's tumor suppressive role." (PMID 22185785, 2011). "Overexpression of ErbB2 has been shown previously to bestow MECs with increased proliferative capacity, and it has also been associated clinically with early stage breast cancer (DCIS)." (PMID 21647371, 2011). "EMT in breast cancer is tightly linked to the triple negative (ER-, PR- and ErbB2-) basal-like breast cancer subgroup and cancer stem cells." (PMID 21915264, 2011). "Some luminal B and the HER-2+ subtypes of breast cancer, which contain gene amplification of ErbB-2, are associated with poor prognosis, aggressive disease, and resistance to some cytotoxic and endocrine therapies." (PMID 21847123, 2011). "Expression of KLF6 was further analyzed in breast cancer tissues overexpressing ERBB2 oncoprotein, which is associated with poor disease prognosis and patient's survival." (PMID 20126619, 2010). "Amplification of ErbB2 is found in 20-30% of breast cancer patients and is associated with poor prognosis." (PMID 21034468, 2010). "The gene BIRC5 on 17q25.3, which encodes the apoptosis inhibitor survivin, co-amplifies with ERBB2 and correlates with high histological grade and a poor prognosis in breast cancer when overexpressed." (PMID 20158880, 2010). "When combining ER, PR and HER2 as variables of breast cancer subtype, ERBB2+ and basal-like subtypes, both contributed to the risk of LN involvement (OR 1.773, 95% CI 1.543–2.037)." (PMID 20543953, 2010). "Overexpression of the epidermal growth factor receptor-related gene ErbB2 occurs in 18% to 25% of patients with breast cancer in Western countries and is associated with a poor prognosis." (PMID 20715159, 2010). "It is well established that overexpression of the ERBB2 amplicon is predominantly associated with the ERBB2 breast cancer subtype." (PMID 20158880, 2010). "The GIPC1 signature is also strongly associated patient survival within the ERBB2+/ER+ (n = 42, P<0.001), luminal B (n = 146, P<0.05) and basal (n = 92, P<0.01) molecular breast cancer subtypes." (PMID 21209904, 2010).
breast cancer (continued). "In human breast cancers, gene expression microarray analysis showed that low Plexin-B1 expression was associated with high histologic grading, ErbB-2 over-expression and a high proliferative index in estrogen receptor-positive breast cancers." (PMID 20858260, 2010). "It is important to note that the TNFAIP1/POLDIP2 module is located outside of the well-known ERBB2 amplicon on 17q12, over-representation of which in the genome is often associated with the occurrence of the ERBB2-positive breast cancer subtype." (PMID 20158880, 2010). "Among the ErbB family, ErbB2 is most directly related to breast cancer and is implicated in breast cancer metastasis." (PMID 21034468, 2010). "PTEN deficiency not only drives breast cancer tumorigenesis but also confers resistance to targeted therapy with trastuzumab, a humanized monoclonal antibody against ErbB2 (also referred to as HER2/neu)." (PMID 22276040, 2010). "ErbB2 is notable for its role in the pathogenesis of breast cancer and as a therapeutic target, and is frequently associated with metastatic disease and tumor progression." (PMID 20727204, 2010). "Amplification of ErbB2 is found in 20-30% of breast cancer patients and is associated with poor prognosis and relapse." (PMID 21034468, 2010). "CCNE1 expression in breast cancer cells has been associated with ER- status, ERBB2 expression, high tumor grade and high proliferation index." (PMID 20932292, 2010). "By use of two independent cohorts of invasive breast carcinomas, our study is, to our knowledge, one of the first to deliver specific methylation profiles associated with basal-like, ERBB2+, luminal A, and luminal B molecular subtypes of breast cancer." (PMID 20920229, 2010). "ErbB2 (HER-2/neu) has been identified as an important regulator of the metastatic potential of breast cancer, which is the principal cause of death." (PMID 21078198, 2010). "HER2/neu (also known as ErbB2) is one of the best characterized oncogenes linked with poor prognosis of breast cancer." (PMID 20650008, 2010). "We have previously demonstrated that the effect of ethanol on the migration/invasion of breast cancer cells is positively associated with their expression levels of ErbB2." (PMID 21034468, 2010). "TXNRD1 and TXNIP are associated with prognosis in breast cancer, and ERBB2 seems to be one of the factors shifting balances of both factors of the redox control system in a prognostic unfavorable manner." (PMID 20584310, 2010). "The present study was designed to investigate the prognostic significance of phosphorylated ShcA in primary breast cancer and its association in the interactions between the ER and ErbB2 pathways." (PMID 24281038, 2010). "Approximately 25–30% of patients with breast cancer belong to a subgroup who overexpress the ErbB2 (HER2) oncogene, and this is associated with a higher risk of disease progression and death." (PMID 20179708, 2010). "The type I insulin-like growth factor receptor (IGF-IR) and ErbB2 (Her-2) are receptor tyrosine kinases implicated in human breast cancer." (PMID 20825649, 2010). "The human epidermal growth factor receptor type-2 (HER2) proto-oncogene (c-erbB-2) is amplified in 15-30% of human breast cancers, causing overexpression of its protein." (PMID 20925963, 2010). "Coamplification of MYC and PVT1 seem to correlate with rapidly growing and progressive breast cancer and has been associated with poor outcome in postmenopausal or ERBB2-positive BC patients." (PMID 20932292, 2010). "This is of interest since over expression of ErbB-2, often caused by gene amplification, characterizes 20-30% of human breast cancers being casually linked to an aggressive clinical course of these tumors and a variable percentage of extra-mammary tumors." (PMID 20565727, 2010).
breast cancer (continued). "The genetic linkage between NR1D1, PBP, and ERBB2 causes co-overexpression of these gene products such that ERBB2-positive breast cancer cells are preprogrammed to depend on fatty acid synthesis for energy production and survival." (PMID 19298655, 2009). "Over-expression of PBP and NR1D1 in ERBB2-positive breast cancer cells causes these cells to store fatty acids at 10 times the level of other breast cancer cells (Kourtidis A, Carkner RD, Eifert C, Brosnan MJ, Conklin DS; unpublished data)." (PMID 19298655, 2009). "We obtained stable MCF10A cells overexpressing wild-type (Wt) Neu/ErbB2 or a constitutively active (CA) variant via retroviral delivery or mammary tumor cells from MMTV-Neu tumors." (PMID 19754954, 2009). "The oncogene ErbB2, overexpressed in 25%–30% of breast cancer, has been shown to disrupt polarity by associating with the Par6 polarity complex." (PMID 19536326, 2009). "hCAP18/LL-37 amplified Heregulin-induced mitogen-activated protein kinase (MAPK) signalling through ErbB2, identifying a functional association between hCAP18/LL-37 and ErbB2 in breast cancer." (PMID 19183447, 2009). "Amplification and overexpression of the tyrosine kinase receptor gene ERBB2 is a hallmark of metastatic development in breast cancer." (PMID 19183447, 2009). "Gene amplification and protein overexpression of the tyrosine kinase receptor ErbB2 is considered a hallmark of metastatic development and poor outcome in breast cancer." (PMID 19183447, 2009). "The TOP2A deletion is associated with increased risk of BC recurrence and death from breast cancer in patient with ERBB2 amplified BC." (PMID 18702822, 2008). "Genomic alterations of the proto-oncogene c-erbB-2 (HER-2/neu) are associated with aggressive behavior and poor prognosis in patients with breast cancer." (PMID 18854030, 2008). "HER2/neu (also called c-erbB2), a cell-surface membrane receptor, has been identified and recognized to be significantly associated with breast cancer recurrence and death in the last two decades." (PMID 18184439, 2008). "Mutated EGFR has been found in a subset of NSCLCs, and ERBB2 is amplified and over-expressed in up to 30% of human breast cancers, which is associated with a poorer clinical outcome." (PMID 19019207, 2008). "The MAM-1 gene expression profile contains clusters that represent the ErbB-2 breast cancer signature and stroma-specific clusters associated with invasive breast cancers." (PMID 18435859, 2008). "Co-amplification of erbB2/neu and topoisomerase IIα has recently been suggested to be able to define a subgroup of high-risk breast cancer patients who benefit the most from anthracycline treatment." (PMID 18493232, 2008). "The ErbB2/Neu/HER2 oncogene is amplified and overexpressed in 20% to 30% of human breast cancer cases, and expression of ErbB2 is associated with aggressive metastatic tumour behaviour, decreased time to clinical relapse and poor prognosis." (PMID 18700973, 2008). "Gene amplification and/or somatic mutations of the HER2/Neu (ErbB2) proto-oncogene occur in approximately 20% of breast cancers." (PMID 17407594, 2007). "Applying our PCT-TC analysis, we achieved an even further stratification of 165 breast cancer patients with the histological types that had been associated with a bad prognosis, ERBB2-positive, Basal and Luminal B groups." (PMID 17206280, 2007). "Since ErbB2 has a role in proliferation of breast cancer cells and Grb7 associates with ErbB2, we are interested in looking at the effects of the Grb7 targeting peptide G7-18NATE-P on proliferation on a variety of different breast cancer cell lines." (PMID 17426702, 2007). "Our data did not support an association between common variation in the ATM, CHEK2 and ERBB2 genes and breast cancer survival or the risk of developing tumours of different characteristics." (PMID 17132159, 2006).
breast cancer (continued). "We used a comprehensive SNP tagging approach using the publicly available HapMap data, complemented by the random selection of SNPs from dbSNP, to determine if common variation in the ERBB2 amplicon is involved in breast cancer susceptibility." (PMID 17117180, 2006). "Both alleles, BRCA2 (N372H) and ERBB2 (V655I), have been associated with different risk of developing breast cancer." (PMID 16438707, 2006). "Until now, common variation in the ATM, CHEK2 and ERBB2 genes has mainly been studied in relation to the overall risk of breast cancer, but the results have been inconclusive." (PMID 17132159, 2006). "We calculated global P values for the association between the tagSNP haplotypes in the ATM, CHEK2 and ERBB2 genes and the risk of tumour-characteristic-defined breast cancer from logistic regression models." (PMID 17132159, 2006). "In comparison with those consistently classified as basal-like (n = 46), the tumors clustered as ERBB2 (n = 12) showed a lower average expression in KRT17, KRT5 and especially GABRP, which has been reported to be associated with ER-/HER2- breast cancers." (PMID 16846532, 2006). "We then assessed the association of the tagSNPs in the ATM, CHEK2 and ERBB2 genes and their haplotypes with breast cancer survival and the risk of tumour-characteristic-defined breast cancer." (PMID 17132159, 2006). "ErbB-2 overexpression, most often caused by gene amplification, can be detected by immunohistochemistry in approximately 30% of breast carcinomas, is associated with an aggressive clinical course, and predictive of a worse prognosis." (PMID 17010186, 2006). "One of the most common genetic aberrations associated with breast cancer is the amplification and overexpression of the ERBB2 proto-oncogene located at chromosome 17, bands q12-21." (PMID 15743507, 2005). "One of the most common genetic alterations associated with human breast cancer is the amplification of the ERBB2 proto-oncogene." (PMID 15743507, 2005). "ERBB2 amplification or overexpression is seen in about 25% of breast cancers and has been associated with metastatic phenotype, endocrine therapy unresponsiveness, and poor prognosis." (PMID 15743501, 2005). "Transgenic mice expressing the activated rat c-neu (with deletion mutations) bear mammary tumors with elevated co-expression of the mutant c-neu/ErbB2 and the endogenous mouse ErbB3-encoded protein." (PMID 16168116, 2005). "We aimed to determine if common polymorphisms (frequency ≥ 5%) in ERBB2 were associated with breast cancer risk in a white British population." (PMID 15743501, 2005). "To clarify the role of ERBB2 in the predisposition to breast cancer, we tested the association of five common polymorphisms (including I655V) with the disease in a large case–control study of white British women." (PMID 15743501, 2005). "Our findings demonstrate that, in breast cancer patients, Akt activation is associated with tumour proliferation and poor prognosis, particularly in the subset of patients with ErbB2-overexpressing tumours." (PMID 15987444, 2005). "The receptor tyrosine kinase ErbB-2 (Her-2/Neu) is overexpressed in 25 – 30% of all human breast cancers, and is associated with a poor prognosis and an increased likelihood of metastasis." (PMID 14710226, 2004). "In this study, we show that ERBB-2 overexpression also causes the cells to acquire other characteristics exhibited by human breast cancer cells, such as anchorage-independent growth and invasion capabilities." (PMID 10682681, 2000). "ERBB2+ breast cancer has an intermediate mutation rate of 50%." (PMID 40191734, 2025). "ERBB2 mutations were identified in 3.4% of breast cancer cases." (PMID 41154672, 2025). "Furthermore, studies that analyzed breast cancer patients according to genetic ancestry showed that a higher IA ancestry fraction is associated with ERBB2/HER2 expression." (PMID 40777119, 2025).